LRFN2 (leucine rich repeat and fibronectin type III domain containing 2)
Description:
Promotes neurite outgrowth in hippocampal neurons. Enhances the cell surface expression of 2 NMDA receptor subunits GRIN1 and GRIN2A. May play a role in redistributing DLG4 to the cell periphery (By similarity).
Synonyms: KIAA1246; SALM1; FIGLER2
Tractability: Antibody: its Gene Ontology location is reachable by antibodies, with high confidence; UniProt places it where antibodies can reach, with medium confidence; UniProt predicts a signal peptide or a membrane-spanning region; the Human Protein Atlas places it where antibodies can reach. PROTAC: its protein half-life has been measured.
Gene: Protein-coding gene on chromosome 6 (40,391,591 to 40,587,364, reverse strand). Ensembl gene ENSG00000156564.
Subcellular location: Membrane; Synapse; Postsynaptic cell membrane
Subcellular location (Human Protein Atlas): Plasma membrane
Pathways (Reactome):
Neuronal System: Synaptic adhesion-like molecules
Gene Ontology:
Biological process: modulation of chemical synaptic transmission; regulation of postsynapse organization
Cellular component: plasma membrane; cell surface; postsynaptic density membrane; membrane; postsynapse; postsynaptic membrane; presynapse; Schaffer collateral - CA1 synapse; synapse
Genetic constraint (gnomAD): Loss-of-function variants: 18 observed, 36.52 expected, observed/expected ratio (o/e) 0.49, 90% interval 0.34 to 0.73. The upper end of that interval is the gene's LOEUF score, 0.73, which puts it in group 2 of 6, group 1 being the genes least tolerant of losing a copy. Missense variants: 1,006 observed, 1,079.5 expected, observed/expected ratio (o/e) 0.93, 90% interval 0.88 to 0.98. Synonymous variants: 556 observed, 478.11 expected, observed/expected ratio (o/e) 1.16, 90% interval 1.08 to 1.25.
Homologues: Orthologues: macaque LRFN2 (99% identical), chimpanzee LRFN2 (99% identical), dog LRFN2 (96% identical), rat Lrfn2 (95% identical), pig LRFN2 (95% identical), guinea pig LRFN2 (95% identical), mouse Lrfn2 (95% identical), rabbit LRFN2 (94% identical), tropical clawed frog lrfn2 (73% identical), zebrafish LRFN2 (67% identical), zebrafish lrfn2b (64% identical). Paralogues in human: LRFN5 (46% identical), LRFN4 (45% identical), LRFN1 (45% identical), LRFN3 (40% identical), SLIT2 (18% identical), SLIT3 (18% identical), LRRN1 (18% identical), SLIT1 (17% identical), LRRN2 (17% identical), LRRN3 (16% identical), TLR9 (16% identical), LINGO1 (16% identical), and 13 more.
Diseases named in the same sentence as LRFN2 in open-access papers:
LRFN2 is named in the same sentence as 32 diseases in open-access papers, as found by Europe PMC text mining. Sharing a sentence is not in itself a finding about the gene and the disease. The quoted sentences say what the papers report.
autism (4 papers, 2017 to 2024). Persistent deficits in social interaction and communication and interaction as well as a markedly restricted repertoire of activity and interest as well as repetitive patterns of behavior. "LRFN2 is increasingly being linked to a range of neurological conditions including antisocial personality disorder, autism, schizophrenia, working memory deficits, and learning disabilities." (PMID 34251337, 2021). "Furthermore, we detect functionally defective LRFN2 missense mutations in autism and schizophrenia patients." (PMID 28604739, 2017). "Here, we show that Lrfn2 knockout mice exhibit autism-like behavioural abnormalities, including social withdrawal, decreased vocal communications, increased stereotyped activities and prepulse inhibition deficits, together with enhanced learning and memory." (PMID 28604739, 2017). "Here the authors show that Lrfn2 regulates excitatory synapse maturation and maintenance, and that Lrfn2 knockout mice exhibit autism-like behaviours as well as enhanced learning and memory." (PMID 28604739, 2017). "We also carried out resequencing analysis of LRFN2 in autism and schizophrenia patients and identified functionally impaired missense mutations." (PMID 28604739, 2017). "LRFN2 knockout mice exhibited autism-like behavioural abnormalities and, similar to SHANK2 and ASB4, could be relevant in terms of pig feeding related behaviors." (PMID 36057580, 2022). "We therefore consider that the behavioural abnormalities in Lrfn2 KO mice may partly mimic the pathophysiological status of autism patients." (PMID 28604739, 2017).
learning disabilities (4 papers, 2017 to 2021). "LRFN2, encoding SALM1, has recently been implicated in learning disabilities, as supported by impaired working memory and executive function in three individuals in a family with a 6p21 autosomal dominant microdeletion (~870 kb) encompassing three genes, including LRFN2." (PMID 29674953, 2018). "Lrfn2/SALM1 is a PSD-95-interacting synapse adhesion molecule, and human LRFN2 is associated with learning disabilities." (PMID 28604739, 2017). "LRFN2 is associated with ASD, learning disabilities, and antisocial personality disorder." (PMID 34795694, 2021).
schizophrenia (4 papers, 2014 to 2024). A major psychotic disorder characterized by abnormalities in the perception or expression of reality. "LRFN2 is also associated with obesity-related traits, cognitive performance, EA, psychiatric conditions such as insomnia and schizophrenia, and multiple cancers (lung cancer, gastric cancer, and squamous cell carcinoma)." (PMID 38706793, 2024). "The amount of LRFN2 transcript in the postmortem brains of individuals with schizophrenia was comparable to that of control subjects." (PMID 28604739, 2017).
Alzheimer disease (3 papers, 2018 to 2025). A progressive, neurodegenerative disease characterized by loss of function and death of nerve cells in several areas of the brain leading to loss of cognitive function such as memory and language. "The LRFN2 gene encodes a synaptic cell adhesion protein in the brain and is related to memory deficits and Alzheimer's disease." (PMID 41473692, 2025). "Similarly, levels of SALM1/LRFN2 proteins were found to be substantially decreased in postmortem brains of patients with neurodegenerative disorders associated with cognitive declines such as Alzheimer’s disease and Parkinson’s disease with dementia." (PMID 29674953, 2018).
cognitive decline (3 papers, 2018 to 2024). "A proteomic study of synaptic markers has shown a strong association of LRFN2 with cognitive decline in an AD population." (PMID 38706793, 2024). "LRFN2 had the highest level of reduction compared to other synaptic proteins in all three forms of dementia, and its loss was strongly associated with rate of cognitive decline." (PMID 34251337, 2021).
Obesity (3 papers, 2022 to 2024). Accumulation of substantial excess body fat. "The LRFN2 gene is expressed in the brain, and has been associated to BMI, T2DM, and obesity-related traits." (PMID 37033211, 2023).
autism spectrum disorder (2 papers, 2018 to 2021). A spectrum of developmental disorders that includes autism, and Asperger syndrome. "Recent genetic studies have linked human LRFN2 to autism-spectrum disorders, working memory deficits, and anti-social personality disorder; moreover, mouse Lrfn2 deficiency results in altered synaptic plasticity and abnormal social behaviors." (PMID 33481887, 2021). "Furthermore, using targeted gene sequencing, this study identified point mutations of the LRFN2 gene in individuals with autism spectrum disorders (ASDs), and demonstrated that a missense mutation inhibits the association of SALM1 with PSD-95." (PMID 29674953, 2018).
Anxiety (1 paper, 2021). Intense feelings of nervousness, tension, or panic often arise in response to interpersonal stresses. "Lrfn2 KO mice also displayed ASD-like behaviors such as social withdrawal, decreased vocal communications, increased repetitive behaviors and prepulse inhibition deficits, but not anxiety-like behaviors." (PMID 34795694, 2021).
diabetic neuropathy (1 paper, 2023). A chronic, pathological complication associated with diabetes mellitus, where nerve damages are incurred due to diabetic microvascular injury involving small blood vessels that supply these nerves, resulting in peripheral and/or autonomic nerve dysfunction. "For diabetic neuropathy, gene GFY (rs4802605), ADH4 (rs4148883), LRFN2 (rs61731010), PKHD1 (rs2499486), SLC11A1 (rs17235409), MATN4 (rs2072788), and PPARA (rs4253772) were associated or contributed to the biological relevance to the pathogenesis of the complication." (PMID 37033211, 2023).
erythrocythemia (1 paper, 2021). "As erythrocythemia can be secondarily caused by increased EPO levels, we measured the serum EPO levels in Lrfn2 KO mice and found that it was significantly decreased (- 6.7%, P = 0.022)." (PMID 33481887, 2021).
esophageal cancer (1 paper, 2022). A primary or metastatic malignant neoplasm involving the esophagus. "Regarding the relationship between LRFN2 and cancer, LRFN2 is known to inhibit esophageal cancer progression via the regulation of the Wnt/β-catenin and NF-κB signaling pathways." (PMID 36428562, 2022). "Its relevance to BC remains unclear, as in esophageal cancer, LRFN2 may be involved in BC progression via the Wnt/β-catenin and NF-κB signaling pathways." (PMID 36428562, 2022).
esophageal squamous cell carcinoma (1 paper, 2019). Esophageal squamous cell carcinoma (ESCC) is a type of esophageal carcinoma (EC) that can affect any part of the esophagus, but is usually located in the upper or middle third. "A recent GWAS has discovered three novel intronic single nucleotide polymorphisms in genes LRFN2 (rs2494938), DNAH11 (rs2285947) and PLCXD2 (rs2399395) that are associated with altered risk of esophageal squamous cell carcinoma (ESCC) among Han Chinese populations." (PMID 31053115, 2019).
pancreatic cancer (1 paper, 2019). "Some studies showed that SALM1/LRFN2 was involved in erythropoiesis and that SALM2/LRFN1 participates in pancreatic cancer cell survival." (PMID 31089399, 2019).
tumor (3 papers, 2017 to 2025). "There were four non-silent mutations in this tumor, all missense SNVs: Lrfn2 R656H, Smyd1 R237Q, Ubn2 Q549K and Wdr11 I46T." (PMID 29029386, 2017). "Tumor-intrinsic leucine-rich repeat and fibronectin type III domain-containing protein LRFN2 suppresses the recruitment and functional transformation of CD8+ T cells by reducing the secretion of pro-inflammatory cytokines and chemokines." (PMID 40438606, 2025). "SPDEF, TRIM3, HSPB1, SPINT1, EPN3, and LRFN2 were significantly highly expressed in the HER2-positive type than in TNBC (p < 0.05), as the HER2-positive type is reported to have a larger tumor size and higher stage." (PMID 36428562, 2022). "Enforced expression of LRFN2 did not alter the survival of tumor-bearing mice (upper left) despite its expression in resulting tumors (upper left)." (PMID 29029386, 2017). "Furthermore, spatially exclusive relationships between LRFN2+ tumor cells and CD8+ T cells, as well as markers such as programmed cell death-1 (PD-1) and T cell factor 1 (TCF-1), have been observed, thereby enhancing tumor resistance." (PMID 40438606, 2025). "Recent studies have found that LRFN2 forms a non-inflammatory tumor microenvironment (TME) in BLCA." (PMID 40438606, 2025). "Indeed, enforced expression of wild-type WDR11 (but not LRFN2, Ubn2, Smyd1) hindered G3 MB development, which is in-line with our hypothesis about its tumor suppressor activity." (PMID 29029386, 2017).
neurodevelopmental disorder (2 papers, 2017 to 2024). A behavioral and cognitive disorder with onset during the developmental period that involves impaired or aberrant development of intellectual, motor, or social functions. "Together with the profound cognitive function deficits, we believe that Lrfn2 KO is a model for neurodevelopmental disorders that conforms to the synapse maturation defect as a cause of ASDs." (PMID 28604739, 2017).
LRFN2 also shares sentences with these, for which no sentence is quoted: dementia (2 papers); Parkinson disease (2); cancer (1); Cognitive impairment (1); depression (1); gastric cancer (1); hyperlipidemia (1); Hypertension (1); immune diseases (1); insomnia (1); Insulin resistance (1); lung carcinoma (1); male infertility (1); schizotypal personality disorder (1); squamous cell carcinoma (1); Stillbirth (1); type 2 diabetes (1).